ALKBH5 (alkB homolog 5, RNA demethylase)
Diseases named in the same sentence as ALKBH5 in open-access papers (continued):
Sharing a sentence is not in itself a finding about the gene and the disease.
ovarian carcinoma (continued). "In addition, to investigate the relationship between M2 macrophages with ALKBH5 and IGF2BP2 in ovarian cancer, two independent datasets from GEO database using CIBERSORT method were searched for further study." (PMID 38637813, 2024). "The small molecules or drugs targeting ALKBH5 or IGF2BP2 were investigated using GDSC and CTRP database, which might help demonstrate the potential drugs that target ALKBH5 or IGF2BP2 in ovarian cancer." (PMID 38637813, 2024). "Taken together, our results could potentially represent the roles of ALKBH5 and IGF2BP2 played in macrophages in ovarian cancer, which might work as the potential immunotherapy biomarkers." (PMID 38637813, 2024). "Surprisingly, in ovarian cancer tissues, the ALKBH5 expression level was similar to that in adjacent nontumor tissues, and its protein level was significantly higher in ovarian cancer tissues than in adjacent tissues." (PMID 38098223, 2024). "Additionally, significant correlations were observed between the methylation of ALKBH5, WTAP, ELAVL1, CDH2 and immunoinhibitors, immunostimulators, and MHC molecules in ovarian cancer using Spearman’s correlation analysis." (PMID 37684273, 2023). "Besides, ALKBH5-mediated mRNA demethylation increases NANOG expression and enhances aggressiveness of ovarian cancer cells." (PMID 35063010, 2022). "ALKBH5 expression is increased in epithelial ovarian cancer in comparison with noncancerous ovarian tissue." (PMID 35063010, 2022). "Moreover, the ectopic expression of ALKBH5 activates the EGFR-PIK3CA-AKT-mTOR signaling pathway and stabilizes BCL 2 mRNA to prevent autophagy of epithelial ovarian cancer cells." (PMID 34491904, 2021). "At the same time, the expression level of ALKBH5 was significantly increased in SKOV‐3 and Ishikawa co‐cultured cells; meanwhile, all the expression levels of NANOG, SOX‐2 and OCT‐4 increased in ovarian cancer tissues, but fell in ovarian cancer cell lines." (PMID 32329191, 2020). "ALKBH5 was shown to regulate the processing of miR-7 in a HuR dependent manner in ovarian cancer and to affect the expression of miR-7 target gene EGFR, which gave us a hint that ALKBH5 might serve as a biomarker or target in the anti-EGFR chemotherapy." (PMID 32209098, 2020). "Ovarian cancer cells cocultured with M2 macrophages showed the increased expression of the molecular toleration-like receptor (TLR4) in the tumour microenvironment (TME), which upregulated ALKBH5 by activating the NF-κB pathway, and eventually promoted ovarian carcinogenesis in the mock TME." (PMID 37194218, 2023). "The results showed that the gene and protein expression patterns of ALKBH5, ELAVL1, and CDH2 were increased in ovarian cancer, while the protein expression of WTAP did not match the gene expression, suggesting gene transcription and translation may be involved in its preservation." (PMID 37684273, 2023). "In ovarian carcinoma, ALKBH5 expression was increased compared to non-cancerous ovarian tissues." (PMID 37007161, 2023). "Elevated ALKBH5 expression has also been shown to contribute to the m6A modification of frizzled class receptor 10 (FZD10) mRNA and to the resistance of ovarian cancer cells to treatment with a poly-ADP ribose polymerase inhibitor, which may also be associated with altered FTO levels." (PMID 35251990, 2022). "Moreover, in ovarian cancer, downregulated FTO and ALKBH5 in PARPi resistance cancer cells also could be decreased PARPi sensitivity." (PMID 34745970, 2021). "The expression pattern of ALKBH5 in epithelial ovarian cancer is not yet fully elucidated." (PMID 30987661, 2019). "However, the expression and function of ALKBH5 in epithelial ovarian cancer have not yet been determined." (PMID 30987661, 2019). "However, the expression and function of ALKBH5 were not elucidated in epithelial ovarian cancer." (PMID 30987661, 2019).
ovarian carcinoma (continued). "The low expression of ALKBH5 mRNA was significantly correlated with PFS and OS, but that with PPS was not significant in any of the ovarian cancer patients." (PMID 30987661, 2019). "No change of global m6A levels in ovarian cancer resistant cells might be due to downregulated FTO, ALKBH5, METTL3, and METTL14." (PMID 34745970, 2021). "Thus, we assumed that ALKBH5, but not IGF2BP2 might participate in regulation the macrophages in ovarian cancer, especially by promoting the M2 polarization of macrophages." (PMID 38637813, 2024).
hepatocellular carcinoma (58 papers, 2019 to 2025). A malignant tumor that arises from hepatocytes. "ALKBH5, an m6A “eraser”, increases radiotherapy resistance in hepatocellular carcinoma (HCC) and GBM by influencing CSCs." (PMID 40823093, 2025). "Research on METTL3, ALKBH5, hepatocellular carcinoma, plant viruses, cancer progression, and Type I interferonthe current focal point and anticipated trend for future investigations." (PMID 38238848, 2024). "Compound 20 m is a potent and selective ALKBH5 inhibitor, stabilising ALKBH5 in human hepatoma cells." (PMID 38545841, 2024). "CircRNA cIARS modulates ferroptosis in hepatic carcinoma by interacting with ALKBH5, and circANRIL modulates ribosomal RNA maturation by circRNA-protein interactions." (PMID 37370086, 2023). "As a special LncRNA, long intergenic non-coding RNA LINC02551, a bona fide m6A target of ALKBH5, was downregulated by ALKBH5 in an m6A dependent manner in hepatocellular carcinoma." (PMID 37365581, 2023). "Up to now, two studies have reported that LncRNA CASC11 and LncRNA GAS5-AS1 can mediate the m6A modification through affecting ALKBH5 in hepatocellular carcinoma and cervical cancer, respectively." (PMID 37365581, 2023). "In this study, we confirmed hypoxia induced upregulation of the ALKBH5 protein in hepatoma cells and observed a correlation between ALKBH5 expression and hypoxia at the clinical and animal levels." (PMID 35982895, 2022). "In Transwell in vitro experiments, we found that the chemotactic ability of hepatoma cells toward THP-1 cells was decreased after silencing ALKBH5 through coculture." (PMID 35982895, 2022). "In contrast, ALKBH5 has been reported to play a tumor-suppressing effect in hepatocellular carcinoma and pancreatic cancer." (PMID 35318440, 2022). "The circRNA cIARS abrogated alkylation repair homologue 5 (ALKBH5)-mediated autophagy inhibition in hepatocellular carcinoma (HCC) by physically interacting with ALKBH5." (PMID 35127685, 2022). "ALKBH5 is downregulated in hepatocellular carcinoma, and it can inhibit tumor proliferation and invasion capacity, depending on the posttranscriptional inhibition of LYPD1." (PMID 35395767, 2022). "To evaluate the effect of ALKBH5 on the tumor immunosuppressive microenvironment, we constructed the mouse hepatoma cell line H22 with stable ALKBH5 knockdown and stable MAP3K8 overexpression." (PMID 35982895, 2022). "The results supported the ability of ALKBH5 to promote malignant behavior in hepatocellular carcinoma." (PMID 35982895, 2022). "ALKBH5 is known to suppress malignant hepatocellular carcinoma cells by epigenetically inhibiting LYPD1 via m6A modification." (PMID 34491904, 2021). "ALKBH5, the demethylase enzyme, has been reported to be highly expressed in various cancers including Hepatocellular Carcinoma (HCC), suggesting its common role in tumor genesis and progression." (PMID 34112124, 2021). "Similarly, ALKBH5 expression in hepatocellular carcinoma (HCC) is linked to poor prognosis." (PMID 40271153, 2025). "The result showed that topics such as METTL3, ALKBH5, hepatocellular carcinoma, plant viruses, cancer progression, clinical application, and IFN-1 reflect good development trends and may be future research hotspots." (PMID 38238848, 2024). "To investigate whether ALKBH5 regulates HDAC4 m6A modifications in HepG2-NTCP hepatoma cells we precipitated methylated HDAC4 mRNA in ALKBH5 silenced cells under hypoxic conditions." (PMID 38227578, 2024). "However, in hepatocellular carcinoma, ALKBH5 downregulates the lncRNA LINC02551, which is associated with the function of the demethyltransferase of ALKBH5." (PMID 38125749, 2023). "In hepatocellular carcinoma, the involvement of the circRNA cIARS in the regulation of ferroptosis through the inhibition of ALKBH5 was demonstrated by rescue experiments to influence cancer progression and represents a key point in the treatment of hepatocellular carcinoma." (PMID 37152286, 2023).
hepatocellular carcinoma (continued). "Using bioinformatics, we predicted the function of ALKBH5 in hepatocellular carcinoma." (PMID 35982895, 2022). "Herein, we established a hepatoma cell model with stable overexpression or knockdown of ALKBH5." (PMID 35982895, 2022). "Therefore, we performed functional analysis of ALKBH5 in hepatoma cells based on single-cell sequencing data." (PMID 35982895, 2022). "Besides, Depmap data based on CRISPR data also showed that silencing ALKBH5 impaired the proliferation of hepatoma cells including Huh-7." (PMID 35982895, 2022). "Therefore, our data confirmed that ALKBH5 promotes proliferation, invasion and PD-L1+ macrophage recruitment in hepatoma cells." (PMID 35982895, 2022). "Furthermore, we observed HBV up-regulates ALKBH5 via the HBx-WDR5-H3K4me3 axis, and ALKBH5 forms a positive feedback loop with HBx to lead to hepatocellular carcinoma progression." (PMID 34112124, 2021). "Research had also found that ALKBH5 regulated the expression of MAP3K8 in hepatocellular carcinoma (HCC) cells and modulated IL-8 expression through the JNK and ERK pathways, promoting macrophage recruitment." (PMID 39220683, 2024). "Understanding the function of AlkB homolog 5, RNA demethylase (ALKBH5) in hepatocellular carcinoma (HCC) holds promise for unraveling new therapeutic strategies for combating this malignancy." (PMID 38501918, 2024). "Bone‐metastasized hepatocellular carcinoma (HCC) derived extracellular vesicles localize to orthotopic HCC cells and target AlkB homolog 5 (ALKBH5) by transferring miR‐3190‐5p." (PMID 37096833, 2023). "In HCC, the malignancy of hepatocellular carcinoma cells is suppressed by ALKBH5 via m6A-guided suppression of the oncogenic driver LYPD1." (PMID 36609413, 2023). "Here, we showed a lincRNA LINC02551 was downregulated by AlkB Homolog 5 (ALKBH5) overexpression in a m6A-dependent manner in hepatocellular carcinoma (HCC)." (PMID 36335087, 2022). "A lower ALKBH5 level was detected in hepatocellular carcinoma (HCC), indicating its prognostic factor of worse survival in HCC patients." (PMID 33790968, 2021). "It is declared that ALKBH5, as an oncogene, enhances macrophage recruitments via the alteration of m6A modification of MAP3K8 and promotes hepatocellular carcinoma metastasis." (PMID 38481816, 2024). "However, an antitumor role of ALKBH5 has been demonstrated in hepatocellular carcinoma (HCC), pancreatic cancer and non-small cell lung cancer (NSCLC)." (PMID 36810108, 2023). "For example, in hepatocellular carcinoma (HCC) cells, cLARS, a type of circRNA, down-regulated ALKBH5 which is a kind of RBP to inhibit tumour cell apoptosis." (PMID 37599427, 2023). "Studies in hepatocellular carcinoma (HCC) and NSCLC have shown that tumor cell RNA modifications, such as those mediated by the N6-methyladenosine (m6A) demethylase ALKBH5, impact TAMs by regulating chemokine expression and thus affecting macrophage recruitment." (PMID 40176140, 2025). "In hepatocellular carcinoma (HCC), high ALKBH5 expression correlated with poor prognosis." (PMID 41562066, 2025). "Notably, a previous report showed that ALKBH5-mediated m6A modification of LY6/PLAUR Domain Containing 1 (LYPD1) is recognized by IGF2BP1 and enhances the stability of LYPD1 mRNA in hepatocellular carcinoma." (PMID 35318440, 2022).
melanoma (54 papers, 2020 to 2025). A malignant, usually aggressive tumor composed of atypical, neoplastic melanocytes. "Small-molecule inhibitors of ALKBH5 significantly enhanced immunotherapy efficacy, and clinical data further linked ALKBH5 expression with immunotherapeutic responsiveness in melanoma patients." (PMID 41562066, 2025). "It was reported that CD58 loss upregulated PDL1 expression in melanoma, in addition, ALKBH5 deficiency enriched m6A modification in the 3’UTR region of PDL1 mRNA and promoted its degradation in intrahepatic cholangiocarcinoma." (PMID 38589927, 2024). "It was also demonstrated that downregulation or mutation of ALKBH5 was correlated with a positive response to PD-1 therapy in patients with melanoma treated with pembrolizumab or nivolumab." (PMID 36960074, 2023). "The low expression of demethylase ALKBH5 was associated with better survival in patients with melanoma." (PMID 35590394, 2022). "Conceivably, harboring ALKBH5 deletions or mutations typically predicts sensitive responses and a favorable efficacy of anti‐PD‐1 treatment in melanoma patients." (PMID 34586737, 2021). "The expression and mutation statuses of the ALKBH5 gene were closely related to the response to immunotherapy in patients with melanoma." (PMID 34956201, 2021). "Mutation or downregulation of the ALKBH5 gene in melanoma patients was associated with positive response to PD-1 blockade by pembrolizumab or nivolumab." (PMID 34956201, 2021). "Of note, the ALKBH5 gene mutation and expression status of ALKBH5 in melanoma tissues are highly correlated with the response to immunotherapy in patients, indicating that ALKBH5 is not only a therapeutic target but also a reliable biomarker in predicting the efficacy of immunotherapy." (PMID 35693795, 2022). "Furthermore, down-regulation of ALKBH5 was associated with positive Pembrolizumab or Nivolumab response to PD-1 blockade in melanoma patients, further demonstrating the role of m6A-modified and immune checkpoints in tumor immune evasion." (PMID 35590394, 2022). "Although ALKBH5 has been proven to correlate with the response to anti-PD1 therapy in melanoma, the association between ALKBH5 expression and response to immunotherapy in patients with COAD still remains unclear." (PMID 34079761, 2021). "Importantly, the level of VEGFA and content of TGF-β1 in the TME are decreased in ALKBH5-deficient melanoma cells." (PMID 34616742, 2021). "Notably, the ALKBH5 gene mutation and expression status of melanoma patients correlate with their response to immunotherapy." (PMID 34188972, 2021). "A lower lactate concentration is accompanied by a smaller proportion of suppressive immune cells (Tregs and MDSCs) in the TIME, which notably harbor ALKBH5 deletions or mutations and typically predict sensitive responses and favorable efficacy of anti‐PD‐1 treatment in melanoma patients." (PMID 34586737, 2021). "Likewise, the deletion of the m6A demethylase ALKBH5 sensitized tumors to cancer immunotherapy, suggesting that ALKBH5 may be a potential target to improve the outcome of immunotherapy for melanomas, CRC, and other underlying cancers." (PMID 36517820, 2022). "And ALK-04, a compound synthesized by in silico screening using the X-ray crystal structure of ALKBH5, was identified as a specific ALKBH5 inhibitor that improved the efficacy of cancer immunotherapy for patients with melanoma." (PMID 40001461, 2025). "ALKBH5 expression levels were augmented in melanoma cells, and MIR205HG downregulation decreased the mRNA levels of ALKBH5 while JMJD2C overexpression promoted the mRNA levels of ALKBH5 (P < 0.01)." (PMID 38252669, 2024). "In favor of our results, previous investigation has uncovered that ALKBH5 expedites the growth and metastasis of melanoma cells via m6A demethylation of forkhead box M1, and confers anti-tumor immunity for melanoma cells." (PMID 38252669, 2024).
melanoma (continued). "ALKBH5 can promote melanoma cell proliferation, colony formation, migration, and invasion and inhibit autophagy in vitro, facilitating tumor growth and metastasis in vivo." (PMID 38481816, 2024). "It has been documented that JMJD2C decreases H3K9me3 level to improve ALKBH5 expression, and ALKBH5 is upregulated in melanoma." (PMID 38252669, 2024). "In melanoma, ALKBH5 suppressed immunity and promoted immune evasion by affecting Tregs and MDSCs, while ALKBH5 knockdown significantly suppressed the expression of Tregs and MDSCs and decreased immune suppression." (PMID 39033180, 2024). "Double knockdown of ALKBH5 and ABCA1 attenuated the inhibition by singly silencing ALKBH5 of melanoma tumor growth in mice reflected by the increase of tumor size and tumor weight." (PMID 38481816, 2024). "Real-time quantitative polymerase chain reaction or Western blot assay showed that MIR205HG, JMJD2C, and ALKBH5 were increased in melanoma cell lines." (PMID 38252669, 2024). "To confirm the impact of ALKBH5 on melanoma cell functions, we upregulated ALKBH5 mRNA level (P < 0.01) and cells with ALKBH5 upregulation were further treated with si-MIR205HG-1 for rescue experiments." (PMID 38252669, 2024). "ALK-04, a small-molecule inhibitor of ALKBH5, functions synergistically with PD-1 inhibitor to suppress the growth of melanoma tumor in vivo." (PMID 36810108, 2023). "ALKBH5 silencing or the use of ALKBH5 inhibitors in tumours improves immunotherapy efficacy, implying that ALKBH5 is a promising target for immunotherapy in melanoma, CRC, and perhaps other cancers." (PMID 36859310, 2023). "Via analyzing clinical data, ALKBH5 was identified as a predictive biomarker of anti–PD-1 blockade ressistance in melanoma." (PMID 36810281, 2023). "We then investigated the expression of common methyltransferases and demethylases like METTL3, METTL14, FTO and ALKBH5 in three melanoma cell lines, which demonstrated that the process of m6A modification was available in melanoma cell lines." (PMID 36324258, 2022). "When a specific ALKBH5 inhibitor ALK-04 was used, the expression of ALKBH5 was down-regulated and the effect of anti-PD-1 therapy was enhanced, indicating that ALKBH5 can be used as a potential therapeutic target for melanoma." (PMID 35590394, 2022). "Accordingly, Alkbh5 knockdown resulted in decreased lactate production in the tumor interstitial fluid of the tumor microenvironment in both melanoma and colon cancer." (PMID 35350378, 2022). "The demethylases, FTO and ALKBH5 reduce the response to anti-PD-1 blockade and accelerate melanoma tumorigenesis by reducing m6A methylation of critical protumorigenic melanoma cell-intrinsic genes." (PMID 35090469, 2022). "Knockdown of Alkbh5 in melanoma and colon cancer cells resulted in m6A-dependent decreases in the stability of Mct4/Slc16a3 mRNA, a regulator of lactate secretion." (PMID 35350378, 2022). "Another eraser, ALKBH5, utilizes different mechanisms but performs a similar function in regulating anti-tumor responses in melanoma, and its expression in tumor cells correlates positively with Treg cell infiltration." (PMID 35296338, 2022). "In contrast, the antitumor effects of ALKBH5 inhibitors, which enhanced the efficacy of cancer immunotherapy, have only been confirmed in melanomas." (PMID 35318440, 2022). "This study also provided evidence for ALKBH5 inhibitors combined with immunotherapy against melanoma." (PMID 36517820, 2022). "In colorectal cancer/melanoma, ALKBH5 accelerated expression of angiogenic genes, such as VEGFA and TGFβ1, which weakened the efficacy of GVAX/anti–PD-1 therapy." (PMID 36291060, 2022). "In colorectal cancer/melanoma, the ALKBH5 inhibitor ALK-04 downregulated expression of VEGFA and TGFβ1, thus inhibiting angiogenesis and enhancing efficacy of anti–PD-1 therapy." (PMID 36291060, 2022).